IL17F (interleukin 17F)
Diseases named in the same sentence as IL17F in open-access papers (continued):
Sharing a sentence is not in itself a finding about the gene and the disease.
psoriasis (continued). "Similarly, the qPCR analysis indicated that the expression of psoriasis-related cytokines, such as IL-17a and IL-17f, was significantly lower in Slc35e1−/− mice than in control animals." (PMID 37296095, 2023). "IL-17F is believed to be generally co-expressed with IL-17A (the two genes are at the same locus), but this concept is being challenged by more recent data, analyzing emigrating cells from psoriasis samples at a single cell level." (PMID 37283755, 2023). "Both Secukimuab and Ixekizumab target IL-17A, while Brodalumab binds with high affinity to the IL17RA subunit, simultaneously inhibiting IL-17A, IL-17F, IL-17C, and IL-17E and providing a > 95% improvement in upregulated psoriasis genes after 12 weeks of treatment." (PMID 38003284, 2023). "However, recent scRNA-seq data showed the possibility that IL-17A producing T17 cells and IL-17F producing T17 cells are different T17 cell subsets in human psoriasis skin." (PMID 36110854, 2022). "The high affinity of brodalumab to human IL-17RA blocks the biological activities of the pro-inflammatory cytokines IL-17A, IL-17C, IL-17E, IL-17F, and IL17A/F heterodimer, resulting in inhibition of the inflammation and clinical symptoms associated with psoriasis." (PMID 36232430, 2022). "By contrast, pruritus in psoriasis patients is often mild or even absent, and the immune mechanism of psoriasis appears to be activated by Th17 cells and is associated with high levels of IL-17A and IL-17F." (PMID 36314037, 2022). "Besides, much higher levels of IL-17F than IL-17A protein have been detected in the serum of patients with psoriasis." (PMID 36614836, 2022). "Considering that almost all IL-17 cytokines (notably IL-17A, IL-17F, IL-17C, and IL-17E) have been shown to play some role in psoriasis pathogenesis, an approach based on receptor blockade, rather than cytokine inhibition, provides a consistent and valuable treatment strategy." (PMID 34201664, 2021). "In psoriasis, IL-17RA plays a key role in pathogenesis based on: (a) IL-17A, IL-17F, and other IL-17 isoforms are involved in disease development; and (b) IL-17RA is essential for signaling of all IL-17 cytokines but IL-17D, whose receptor has not been identified to date." (PMID 34201664, 2021). "As such, CLA+ memory T cells should be considered an important source of IL-17F in psoriasis." (PMID 34778294, 2021). "However, its principal homolog, IL-17F, has been also proved to be increased in lesional skin and blood from psoriasis patients." (PMID 34778294, 2021). "Early clinical data in patients with psoriasis, in those with psoriatic arthritis, and from the Phase 2 studies in psoriasis, psoriatic arthritis, and ankylosing spondylitis, are encouraging and support the targeted approach of dual neutralization of IL-17A and IL-17F." (PMID 32973785, 2020). "Furthermore, brodalumab, which is a human monoclonal antibody human anti-IL17RA, a pan inhibitor of IL-17A, IL-17F, and IL-25 is currently used in the treatment of psoriasis where shows a complete clearance of moderate-to-severe psoriasis." (PMID 33574815, 2020). "Even though IL-17A and IL-17F are the most important of the IL-17 family members involved in the pathogenesis of psoriasis, IL-17E is also increased in keratinocytes from the psoriasis plaque and seems to play a proinflammatory role, as it is implicated in macrophage activation." (PMID 30744173, 2019). "While the combined inactivation of epidermal GR and MR is not sufficient to cause spontaneous psoriasis it contributes to sustained inflammation (e.g., increased Il17f levels) and ultimately increases the susceptibility of DKOs to this disease." (PMID 29789551, 2018). "Despite that, no specific polymorphisms in the IL-17F gene have so far been associated with psoriasis susceptibility, although the IL-17F polymorphism rs763780 was linked to a better response to anti-TNF therapy." (PMID 30127781, 2018).
psoriasis (continued). "IL-17F might contribute to skin manifestations and comorbidities of psoriasis in a tissue-specific fashion." (PMID 30127781, 2018). "In this article, the immunologic role of IL-17 in psoriasis and psoriatic arthritis (PsA) pathogenesis, including its role in innate and adaptive immunity, and the rationale for targeting IL-17A, IL-17F, and IL-17 receptor A in the treatment of psoriasis and PsA, are reviewed." (PMID 30109481, 2018). "This article reviews the immunologic role of interleukin (IL)-17, the major effector cytokine in the pathogenesis of psoriatic disease, along with the rationale for targeting the IL-17 cytokine family (IL-17A, IL-17F, and IL-17 receptor A) in the treatment of psoriasis and psoriatic arthritis." (PMID 30109481, 2018). "We subsequently investigated whether neutrophils isolated from patients with active psoriasis could express/produce IL-17A, IL-17F, and/or IL-17RC mRNA, either constitutively or upon incubation for 20 h with IFNγ plus LPS, R848, or IL-17A." (PMID 29719541, 2018). "IL-17A and IL-17F are clinically validated mediators of psoriasis." (PMID 30013558, 2018). "In some diseases, such as psoriasis and asthma, IL-17F plays a more prominent role." (PMID 28210632, 2017). "Hallmark pathways of psoriasis were analysed and among the cytokines IL-17A and IL-17F were elevated in the absence of IL-12Rβ2." (PMID 27892456, 2016). "In light of that, a natural compound like RSV, which might increase the RXR gene expression and decrease IL-17A, IL-17F and IL-19 gene expression in psoriasis-affected skin, could be an interesting new treatment modality in human clinical trials." (PMID 25965695, 2015). "In psoriasis IL-17A, IL-17F, IL-22 and IL-20 act on keratinocytes leading to epidermal hyperplasia." (PMID 25153527, 2014). "And interestingly, IL-17F expression increased more markedly than IL-17A in IMQ-treated mouse skin, indicating that IL-17F may have a greater contribution to IMQ-induced psoriasis-like inflammation." (PMID 23825622, 2013). "Furthermore, S100A8 and S100A9 may inhibit psoriasis by prohibiting the synthesis of IL-17A and IL17-F." (PMID 40540498, 2025). "Conversely, BT patients showed a distinct cytokine profile characterized by significantly reduced levels of IFN-γ, IL-2, IL-17F, and IL-22 compared to UT patients, highlighting the potent immune-modulating effects of biological treatments in attenuating pro-inflammatory pathways in psoriasis." (PMID 39769151, 2024). "However, the dominant immune response in psoriasis is T helper 17 (Th17), whose characteristic cytokines are interleukin 17A (IL-17A), interleukin 17F (IL-17F), interleukin 21 (IL-21), interleukin 22 (IL-22), interleukin 29 (IL-29), interleukin 8 (CXCL-8), and tumor necrosis factor α (TNF-α)." (PMID 38001807, 2023). "Finally, early clinical studies with bimekizumab, a dual IL‐17A and IL‐17F neutralizing antibody, have shown rapid and profound clinical responses in psoriasis 21 and PsA 20 patients suggesting an unappreciated role for IL‐17F in addition to IL‐17A in promoting inflammation." (PMID 31850514, 2020). "However, looking on the effects of cytokines highly relevant in the pathogenesis of psoriasis, i.e., IL-17A, IL-17F, IL-1α, or TNF, on S100A8 or S100A9 expression in keratinocytes we found strong effects on mRNA induction for both genes most pronounced for IL-17A > IL-17F > IL-1α > TNF." (PMID 33643287, 2020). "However, such research on psoriasis is still scarce, possibly because the IL17F gene has not been identified as a susceptibility locus in studies conducted on Western populations." (PMID 31831764, 2019). "Although the absence of GR and MR in keratinocytes did not cause spontaneous psoriasis per se, we detected constitutive upregulation of several genes contributing to the disease such as Il17f, Il22, and Il23 in vehicle-treated DKO skin relative to single KO or CO (and data not shown)." (PMID 29789551, 2018).
psoriasis (continued). "In fact, in a mouse model of imiquimod-induced psoriasis-like inflammation, topical curcumin was demonstrated to improve the skin lesions with an effect comparable to that of clobetasol and to significantly decrease the cutaneous levels of IL-17A, IL-17F, IL-22, IL-1β, IL-6, and TNF-α mRNA." (PMID 26090395, 2015). "Brodalumab, a monoclonal antibody binding to IL-17 receptor A and blocking IL-17A, IL-17C, IL-17F, IL-17A/F, and IL-17E (also known as IL-25), got the FDA approval for adult psoriasis in 2017." (PMID 41481132, 2026). "Bimekizumab, the group’s newest representative, which blocks IL-17A and IL-17F, received FDA approval for the treatment of psoriasis in adults in 2023." (PMID 41481132, 2026). "Contrarily, after Guselkumab withdrawal, increases in serum levels of IL-17A, IL-17F, and IL-22 lagged behind PASI worsening, indicating they are poor predictors of psoriasis flare-ups." (PMID 40699767, 2025). "Based on the available evidence regarding the role of IL17 in psoriasis and PSA, four therapeutic agents against IL-17A, IL17F, or its receptor have been developed: secukinumab, ixekizumab, brodalumab, and bimekizumab." (PMID 39459016, 2024). "A previous report showed that the Th17 family of cytokines (IL-17A and IL-17F) secreted by skin contained infiltrating γδT cells and RORγt+ innate lymphocytes, which promoted the initiation of IMQ-induced psoriasis." (PMID 38444844, 2024). "Mice with TPA-induced psoriasis showed increased gene expression of both the Th17 transcription factor, RORC, and Th17-produced cytokines, Il17a, Il17e, Il17f, and Il22, in the ear tissue compared with those in normal mice." (PMID 39765869, 2024). "The present study showed that, in this group of psoriasis patients, biological therapies decrease serum levels of the proinflammatory cytokines TNF-α, IL-23 and IL-17F." (PMID 39057098, 2024). "We examined the expression of cytokines previously reported to be involved in psoriasis, and found that IL17A, IL17F, IL26, CCL20, CXCL13, IL22, and IL23R were specifically expressed by Tc17 cells." (PMID 37308489, 2023). "Besides, IL-17F may also play a role in the recurrent course of psoriasis." (PMID 37283755, 2023). "Statistically significant correlations were also observed between baseline IL-17A, IL-17F, and IL-22 levels and baseline PASI score as well as between IL-17A and IL-17F levels and BSA affected by psoriasis." (PMID 37587493, 2023). "In the analysis of significantly expressed genes between psoriasis and normal skin, IL17RC was considered as the most significantly overexpressed gene among the IL17 family members, followed by IL17RD, IL17RA, IL17F, and IL17RE." (PMID 36009523, 2022). "An earlier report showed that Th17 family of cytokines (IL-17A and IL-17F) secreted by skin contained infiltrating γδ T cells and RORγt+ innate lymphocytes, which promoted the initiation of IMQ-induced psoriasis." (PMID 35663991, 2022). "In contrast, 983EVs treatment only significantly decreased IL-6, IL-17F, IL-36γ, and IL-36R, while the cytokines IL-36α and IL-36β were overexpressed compared to the only IMQ-induced psoriasis skin." (PMID 34884834, 2021). "The IL-17 cytokine family consists of 6 members, A–F, but only two have a pathogenetic role in psoriasis, IL17-A, and IL-17F." (PMID 34829740, 2021). "Our present study shows that IL-23 acts directly on macrophages to induce IL-17A, IL-17F, IL-22 and IFN-γ productions which likely promote the severity of psoriasis-like dermatitis in mice." (PMID 29508278, 2018). "Further validation by RT-PCR confirmed that IL-23 directly acted on macrophages, promoting the levels of IL-17A, IL-17F, IL-22, and IFN-γ, which may contribute to the severity of psoriasis in mice." (PMID 41383588, 2025).
psoriasis (continued). "Bimekizumab treatment completely reversed the levels of cytokines/chemokines, anti‐microbial peptides, or proliferation‐related molecules, such as CXCL8, CCL20, IL‐17A, IL‐17F, IL‐17C, keratin 16, IL‐36γ, DEFB4, or S100A7, in psoriasis lesional skin to the levels of non‐lesional skin." (PMID 38482898, 2024). "Here, we investigated the expression of psoriasis-related cytokines (TNF-α, IL-6, IL-22, IL-23, IL-17A, IL-17E, IL-17F, IL-4 and IL-10) in the inflamed skin after mannan exposure at the peak (day 4) and the end (day 7) of psoriasis with/without inhibitor(s) treatment." (PMID 38444844, 2024). "Although the role of IL-17F in psoriasis immunopathogenesis has not been fully clarified, determining the variants on this gene has great importance in terms of creating patient-specific treatment options." (PMID 38331704, 2024). "Mice lacking adiponectin develop severe psoriasis-like dermatitis and elevated levels of the Th17-related cytokines IL-17A, IL-17F, and IL-22." (PMID 36675592, 2023). "In addition, T cells expressed IL17A, IL17F, and IL22 that, coupled with their receptors expressed by myeloid cells and keratinocytes, are known to promote inflammation in psoriasis." (PMID 37308489, 2023). "Although anti-IL-17A monoclonal antibody does not directly target IL-17F, the expression of IL17F was also decreased in the CD161+ T-cell cluster in psoriasis lesional skin after IL-17A blockade (p < 0.05)." (PMID 37781383, 2023). "While head-to-head trials have shown dual blockade of IL-17A and IL-17F to be superior to biologic targeting IL-17A, IL-12/23, TNF-α in patients with psoriasis, further data is required to confirm whether this finding replicated in patients with PsA." (PMID 37731935, 2023). "In addition to the cytokines noted above such as IL17F (0.967), and CXCL13 (0.325), this set contained identified psoriasis-specific genes with less established functional roles, such as ARHGEF12 (0.303), ENTPD1 (0.628), LAYN (0.122) and HAVCR2 (0.560)." (PMID 35958578, 2022). "Of considerable interest, the correlation matrix revealed a distinct cytokine panel where cytokines (IFN-γ, IL-18, TNF-α, IL-12B, IL-17A, IL-17F, and IL-22) were positively correlated with each other in psoriasis patients but not in healthy controls." (PMID 36118416, 2022). "In particular, serum levels of IL-17A were strongly correlated with IL-1α, IL-15, IFN-γ, IL-18, TNF-α, IL-12B, IL-17F, and IL-22 in psoriasis but not in healthy controls." (PMID 36118416, 2022). "After four weeks of adalimumab treatment, we showed that there was no decrease in protein levels of IL-17A and IL-17F or their receptors in synovium and skin in our cohort of PsA patients with mild psoriasis." (PMID 35203534, 2022). "Notably, CA-induced IL-17F and IL-17A levels in CLA+T cells were significantly higher in cocultures from guttate psoriasis compared to those of plaque psoriasis." (PMID 33546306, 2021). "The importance of IL-17F in psoriasis development became more evident in mice lacking Il17f gene, which exhibited a more pronounced decrease in acanthosis than mice lacking Il17a." (PMID 34201664, 2021). "Therefore, we used RT-PCR to assess the mRNA levels of inflammatory cytokines, such as IL-6, TNF-α, IL-17A, and IL-17F, in skin tissues of mice with IMQ-induced psoriasis." (PMID 33995368, 2021). "In vivo studies showed that PSORI-CM02 markedly reduced angiogenesis in the skin of mice with IMQ-induced psoriasis, while significantly rebalancing antioxidant/oxidant levels; inhibiting the production of IL-6, TNF-α, IL-17A, and IL-17F; and repressing the synthesis of angiogenic mediators." (PMID 33995368, 2021). "In addition, IL-23 promoted the expression of IL-17A, IL-17F, IFN-γ, and IL-22 in M0 macrophages, and IL-23-treated M0 macrophages significantly enhanced psoriasis-like dermatitis in the mouse model." (PMID 33681365, 2021).
psoriasis (continued). "Of particular note is the acute up-regulation of Il17f (63-fold), in line with the central role of Stat3 in Th17-mediated pro-inflammatory responses and its implication in dermal disorders including HIES and psoriasis." (PMID 33332446, 2020). "Th17 cells exert an effect by secreting IL-17A, IL-17F, IL-26, and TNF in psoriasis, forming a feedforward inflammatory network with KCs, activating STAT-1 and NF-κB signaling pathway, and inducing keratinocytes (KCs) to secrete several pro-inflammatory factors." (PMID 32377228, 2020). "Interestingly, adaptive T-cell-derived cytokines IL17A, IL17F, IL17C, IL26, IFNG, IL4, and IL10 show comparable levels in skin biopsies from paradoxical and classical psoriasis." (PMID 29295985, 2018). "Several cytokine genes with overall low expression but high differential effect in psoriasis (IFNG, IL12B, IL17F, and IL22) displayed higher magnitude changes with cDNA than with cRNA hybridization, whereas the highly expressed gene IL1F9 showed a higher magnitude change with cRNA hybridization." (PMID 23308107, 2013). "It is believed that IL17F may play a role in the development of psoriasis and psoriatic arthritis, but its effects are not as pronounced as those of IL17A." (PMID 37238999, 2023). "Similarly, we show that also neutrophils isolated from patients with active psoriasis do not express IL-17F, IL-17B, IL-17C, IL-17D, and IL-17E as well as IL-17RC mRNA when activated by R848, IFNγ plus LPS, and IL-17A in vitro." (PMID 29719541, 2018). "Moreover, mRNA levels of IL-17F increased more dramatically than IL-17A, indicating that IL-17F may play a more important role than IL-17A in IMQ-induced psoriasis-like inflammation." (PMID 23825622, 2013). "While Th17 cells and associated molecules, such as IL-17A, IL-17F, IL-22, and tumor necrosis factor (TNF-a), are known to be elevated in serum and psoriatic skin lesions, recent research suggests that Th17 cells are not the primary source of these pathogenic cytokines in psoriasis." (PMID 38791423, 2024). "On the other hand, the ATCC12228EVs treatment decreased the mRNAs skin expression of VEGF-A, IL-6, KC, IL-17F, IL-23, and the IL-36 family members IL-36γ and IL-36R, compared to the IMQ-induced psoriasis skin mice with no EV treatment." (PMID 34884834, 2021). "This indicates that IL-19 and IL-24, rather than IL-22, IL-17A or IL-17F, were responsible for the late stage (day 10) keratinocyte hyper-proliferation and acanthosis in the IMQ-induced psoriasis mouse model during anti-IL-10 treatment." (PMID 34616394, 2021). "Moreover, the expression levels of other cytokines, including IL-17F, IL-23, IFN-γ, and TNF-α, were of no corresponding relationship with the states of mouse psoriasis-like phenotype." (PMID 34881280, 2021). "Likewise, Th17-driven psoriasis was diagnosed in only two of our patients, each of whom lacked autoantibodies to IL17A, IL17F, and IL22 (our unpublished data)." (PMID 27426947, 2016).